MLLT10P1 (MLLT10 pseudogene 1)
Synonyms: bA348I14.3; formerly MLLT10L
Gene: Transcribed processed pseudogene on chromosome 20 (30,403,123 to 30,403,384, reverse strand). Ensembl gene ENSG00000238151.
Diseases named in the same sentence as MLLT10P1 in open-access papers:
MLLT10P1 is named in the same sentence as 2 diseases in open-access papers, as found by Europe PMC text mining. Sharing a sentence is not in itself a finding about the gene and the disease. The quoted sentences say what the papers report.
breast carcinoma (1 paper, 2024). "The non-pseudo gene version of MLLT10 has been documented to be a promoter of tumor cell proliferation, migration, and invasion in NSCLC cell lines, and MLLT10P1 is commonly mutated in breast cancer patients." (PMID 38797520, 2024).
MLLT10P1 also shares sentences with these, for which no sentence is quoted: tumor (1 paper).